OR51V1 (olfactory receptor family 51 subfamily V member 1)
Description:
Odorant receptor.
Synonyms: OR51A12; OR11-36
Gene: Protein-coding gene on chromosome 11 (5,199,735 to 5,200,682, reverse strand). Ensembl gene ENSG00000176742.
Subcellular location: Cell membrane
Pathways (Reactome):
Sensory Perception: Expression and translocation of olfactory receptors
Genetic constraint (gnomAD): Loss-of-function variants: 16 observed, 17.34 expected, observed/expected ratio (o/e) 0.92, 90% interval 0.62 to 1.4. The synonymous counts are far from expectation, so gnomAD's model fits this gene poorly and the ratio says little. Missense variants: 461 observed, 393.31 expected, observed/expected ratio (o/e) 1.17, 90% interval 1.09 to 1.27. Synonymous variants: 183 observed, 146.44 expected, observed/expected ratio (o/e) 1.25, 90% interval 1.11 to 1.41.
Homologues: Orthologues: chimpanzee OR51V1 (98% identical), macaque OR51V1 (95% identical), pig OR51V1 (83% identical), rabbit OR51V1 (78% identical), dog OR51V1B (77% identical), rat Or51v14 (74% identical), rat Or51v8b (74% identical), mouse Or51v8 (74% identical), rat Or51v8 (74% identical), mouse Or51v14 (73% identical). Paralogues in human: OR51L1 (52% identical), OR51G2 (51% identical), OR51G1 (51% identical), OR51B5 (51% identical), OR51Q1 (50% identical), OR51B2 (50% identical), OR51B6 (48% identical), OR51F2 (47% identical), OR51C1 (47% identical), OR51M1 (47% identical), OR51A4 (47% identical), OR51B4 (46% identical), and 39 more.
Diseases named in the same sentence as OR51V1 in open-access papers:
OR51V1 is named in the same sentence as 1 disease in open-access papers, as found by Europe PMC text mining. Sharing a sentence is not in itself a finding about the gene and the disease. The quoted sentences say what the papers report.
colon adenocarcinoma (1 paper, 2022). "Mutations of SKIDA1, CLK1, NSFL1C, OR2A5, EDEM3, and OR51V1 were associated with significant deregulation of DDX20 gene expression pattern in colon adenocarcinoma patients." (PMID 36011315, 2022).